METTL21C (methyltransferase 21C, AARS1 lysine)
Description:
Protein-lysine N-methyltransferase using S-adenosyl-L-methionine as methyl donor. Mono-di and trimethylates 'Lys-943' of AARS1.
Synonyms: C13orf39; LOC196541
Tractability: Small molecule: a structure with a bound ligand is known.
Gene: Protein-coding gene on chromosome 13 (102,685,747 to 102,695,044, reverse strand). Ensembl gene ENSG00000139780.
Subcellular location: Nucleus; Cytoplasm
Gene Ontology:
Molecular function: heat shock protein binding; protein binding; protein-lysine N-methyltransferase activity; protein methyltransferase activity
Cellular component: cytoplasm; nucleus; protein-containing complex
Genetic constraint (gnomAD): Loss-of-function variants: 17 observed, 25.29 expected, observed/expected ratio (o/e) 0.67, 90% interval 0.46 to 1.01. The upper end of that interval is the gene's LOEUF score, 1.01, which puts it in group 4 of 6, group 1 being the genes least tolerant of losing a copy. Missense variants: 312 observed, 320.68 expected, observed/expected ratio (o/e) 0.97, 90% interval 0.89 to 1.07. Synonymous variants: 125 observed, 127.17 expected, observed/expected ratio (o/e) 0.98, 90% interval 0.85 to 1.14.
Homologues: Orthologues: chimpanzee METTL21C (99% identical), macaque METTL21C (96% identical), dog METTL21C (84% identical), guinea pig METTL21C (83% identical), rabbit METTL21C (83% identical), pig METTL21C (78% identical), rat Mettl21c (78% identical), mouse Mettl21c (75% identical), tropical clawed frog mettl21c (52% identical), zebrafish mettl21cb (41% identical), zebrafish mettl21ca (38% identical). Paralogues in human: METTL21EP (41% identical), METTL21A (25% identical), EEF1AKMT3 (25% identical), METTL23 (21% identical), VCPKMT (21% identical).
Diseases named in the same sentence as METTL21C in open-access papers:
METTL21C is named in the same sentence as 1 disease in open-access papers, as found by Europe PMC text mining. Sharing a sentence is not in itself a finding about the gene and the disease.
METTL21C shares sentences with these, for which no sentence is quoted: osteoporosis (1 paper).